CCL5 (C-C motif chemokine ligand 5)
Diseases named in the same sentence as CCL5 in open-access papers (continued):
Sharing a sentence is not in itself a finding about the gene and the disease.
infection (continued). "In the brains infected with Pigeon04, mRNA expression levels of Mx1, OAS, IL6, IL1β and CCL5 were at least 17 fold higher than those of respective genes in the infected lungs on day 5 post infection when this virus almost similarly replicated in the lungs and brains." (PMID 21826229, 2011). "In our model, some chemokines reported to be part of the "1st and 2nd waves" of chemokine expression by DC cells, specifically Xcl1, Cxcl9, Cxcl16, Ccl1, Ccl2, Ccl3, Ccl4, Ccl5, Ccl7 and Ccl8 are expressed at increased levels in lung i.n. samples at 3 weeks post-infection." (PMID 20942964, 2010). "At the late phase of infection; induction of IL-8, CCL-5/RANTES, and CXCL-10/IP-10 occurred." (PMID 21108843, 2010). "Also, X4LAI.04 infection of tissues treated with flagellin resulted in an increase of CCL5 secretion." (PMID 20862220, 2010). "Additionally, severe influenza virus infection was associated with hypercytokinemia, including increased cytokine (IFNβ, TNF, IL-10 and IL-12p70) and chemokine (MCP-1 (CCL2), KC (CXCL1), IP-10 (CXCL10) and RANTES (CCL5)) levels in the severe infection group at 7 dpi." (PMID 41285788, 2025). "Therefore, monitoring CCL5 levels could predict infection severity and be applied to inform treatment strategies." (PMID 41155463, 2025). "Cluster 1 was more heterogenous and lacked a distinct transcriptional profile, whereas Type I IFN (Isg15, Ifi206, Ifit3, Ccl5) and proliferative signatures (Cdk1, Mki67, Tuba1b) were observed in clusters 3 and 5, respectively, whose numbers remained stable between days 7 and 14 after infection." (PMID 39989461, 2025). "In addition, higher levels of CCL2/MCP-1, IL-6, and Macrophage inflammatory protein-1 (CCL4/MIP-1β) and decreased levels of Regulated upon Activation, Normal T-cell Expressed and Secreted (CCL5/RANTES) are observed in the chronic phase of infection and arthritic cases." (PMID 38543735, 2024). "The direct interaction or infection of eosinophils by RSV may explain their altered immune response as activated eosinophils secrete proinflammatory cytokines like CCL5, IL-6, and MIP-1α after viral interaction resulting in a proinflammatory milieu and increased influx of proinflammatory cells." (PMID 37896776, 2023). "Additionally, RANTES (CCL5) is a powerful pro-inflammatory mediator of the CC chemokine family that regulates mobilization and, in certain cases, promotes immune cell survival in areas of injury and infection." (PMID 35038337, 2022). "Therefore, the observed inhibition of CCL5 by the parasite, may strongly contribute to the establishment of the infection." (PMID 34832536, 2021). "We therefore wondered whether CCL5 expression would change in our model upon LCMV-WE infection." (PMID 32973762, 2020). "Hence, we quantified the expression of various immunity-related genes regulated by NF-κB: IFNß, CXCL2, TNF, CCL5 and CXCL10 in the brain of mice from two genetic backgrounds, at late stage of the infection by Tha or the isogenic Th4M virus mutated on the positions 77, 100, 104, 110 of the M protein." (PMID 29084252, 2017). "Therefore, TgCyp18-mediated CCL5 production might contribute to macrophage migration to the site of infection and the transport of T. gondii-infected cells to the liver." (PMID 24661782, 2014). "In addition, the rapid induction of inflammatory genes such as CCL5 could attract innate immune cells to clear local infection and possibly increase migration of DCs to draining LNs for the initiation of the adaptive response." (PMID 25474532, 2014). "However, a limited protective role of Met-CCL5 was observed at the late stage of infection." (PMID 25182681, 2014). "The induction of transcription of the monocyte-attracting cytokine CCL5 in human cells fits nicely with our observation of infiltrating monocyte and monocyte-derived cells in mice, making it likely that monocyte-derived cells are similarly attracted to the site of infection in humans." (PMID 25474532, 2014).
infection (continued). "Infection of rhesus (Macaca mulatta) or cynomolgus (Macaca fascicularis) macaques with pathogenic SIV leads to the induction of multiple inflammatory chemokines in lymph nodes and spleen including: CXCL8; CXCL9, CXCL10, and CXCL11; CCL3, CCL4, CCL5; CCL2; CCL19; and CCL20." (PMID 19149556, 2009). "Conversely, the KLRB1+ cluster (cytokine-producing cluster), enriched for cytokine/chemokine genes (CCL5, IFNG, IL32), were depleted during infection." (PMID 41544143, 2026). "Antagonization of CCR5 can prevent the migration of immune cells such as T cells, macrophages, and dendritic cells into tissues in response to infection or chemoattraction by CCR5 ligands CCL3, CCL4, CCL3L1, and RANTES/CCL5." (PMID 39908288, 2025). "Differential expression analysis in this dataset showed a significant upregulation of four core genes (CCL5, PTGS2, HIF1A, and CLEC4E) in the infection group." (PMID 41039310, 2025). "Under the same infection conditions, Q3G treatment significantly reduced production of IFN-β1, IL-6, and CCL5 (RANTES) in both MR766- and BR15-infected cells." (PMID 40732762, 2025). "Infection also boosted the expression of the CXCL2, CCL2, CCL3, and CCL5 chemokines in female mice, while only CCL2 and CCL3 expression increased in males." (PMID 40143355, 2025). "Our results indicated that infection induced the expression of proinflammatory mediators IFN-γ, CCL5, CXCL1, and IL-6 only in the brain." (PMID 39907280, 2025). "In neonatal Swiss mice, USUV infection led to an increase in typical neuroinflammatory cytokines, including IL-6, CCL3, CCL4, CCL5, CXCL9, and CXCL10, with CXCL10 being upregulated to the highest level in this model." (PMID 39907280, 2025). "For this, we measured the quantity of CCL3, CCL5, and CCL4 in the culture supernatants of macrophages infected with HIV and treated with P3DEX or DEX at 24, 48, and 72 h post infection." (PMID 40077760, 2025). "In our previous studies using age/IP-dose matched C3H/HeJ, we found that CCL5/RANTES was increased in serum at 24h and 72h post sublethal infection." (PMID 40445994, 2025). "The infection induced G-CSF and CCL2 on 3 dpi, while CCL5 increased compared with mock infected by 7 dpi." (PMID 40854598, 2025). "Secreted CCL3, CCL4, CCL5, CXCL10, IFN-γ, IL-10, and VEGF were also significantly elevated in LCLs but at lower levels than in de novo infection." (PMID 40359016, 2025). "DCs also express various chemokines, such as CCL2, CCL5, and CXCL10, which aid in recruiting monocytes and DC precursors from the circulatory system to the site of infection, further intensifying the local immune response." (PMID 40872644, 2025). "The factors secreted by the parasite, during the chronic form of infection, stimulate the production of interleukin 12 from dendritic cells and macrophages, as well as the interaction between chemokines, such as CCL4, CCL5 and CCL3." (PMID 40855457, 2025). "Early in infection, M3 decreased the expression of CXCL10 and CCL5 mRNAs, whereas BXA also increased their expression, indicating that these mRNAs, which are targets for M3, can be a source of m7G caps." (PMID 39601535, 2025). "DCs also attract CCR5+ CD8+ T cells to the site of infection by secreting chemokines such as CCL3, CCL4, and CCL5, enhancing the local immune response." (PMID 40872644, 2025). "Results showed elevated levels of pro-inflammatory cytokines such as TNF-α, IL-6, IL-1β, and chemokines CCL5 (RANTES), and IP-10 (CXCL10) after infection with rHPh-TX H5N1." (PMID 40712003, 2025). "We noted that infection in female TLR7ko mice boosted IFNG, CCL2, CCL3, and CCL5 expression, although significantly less compared to the female WT group, but these responses were completely blunted in TLR7ko male mice." (PMID 40143355, 2025). "Although the expression of CCL2, CCL5 and TNF was not as robust as IFN-β, there was a pattern of activation after infection, which was mildly inhibited by G140 for CCL2 and CCL5." (PMID 41139159, 2025).
infection (continued). "Macrophages derived from STS mice produced higher levels of several soluble factors, including CCL5/RANTES, G-CSF, TNF alpha, and IL-6, than macrophages from CcS-11 mice even before infection." (PMID 39875898, 2025). "Infection upregulates proinflammatory cytokines such as TNF-α and IFN-γ and chemokines such as CCL2/MCP-1, CCL3/MIP-1α, and CCL5/RANTES, while downregulating the astrocytic glutamate transporter, GLT-1." (PMID 40743275, 2025). "Seven-day old BALB/c mice were infected intranasally with RSV; 20 μg of CCL5 or CXCL10 in 20 μl were given on days 7, 8 and 9 after infection." (PMID 39749186, 2024). "As expected, we observed an increase in neutrophil, monocyte, and NK cell recruitment cytokines CXCL10, CCL5, and IL-15 during SEOV infection in Cas9 WT control HUVEC." (PMID 39585900, 2024). "By bonding with particular chemokines, such as CCL3, CCL4, CCL5, CCR1 facilitates cell chemotaxis, directing immune cell migration towards inflammatory or infection sites, a function vital for initiating and modulating immune responses." (PMID 39931101, 2024). "Upon infection with Sendai virus (SeV), ectopic overexpression of EGLN1 significantly induced the expression of IFN-β, CXCL10, and CCL5 in HEK293T cells." (PMID 38670937, 2024). "At 72 h post‐infection, these cytokine/chemokine levels shifted with significantly lower IFNγ and IL‐4, significantly higher IL‐5, IL‐10, IL‐17a, and CCL‐5/RANTES, and comparable IL‐2 and TNFα levels." (PMID 37990641, 2024). "The infection induced an increase of the gene expression of the chemokine CCL5 and the cytokine IFNγ (approximately 250 times) in the IPP of lambs during the resolution of infection, which we also observed in the distal jejunum and JPP." (PMID 38756777, 2024). "Infection of BRB with ZIKV leads to the generation of IL-1β, IL-6, IFN-α, IFN-β, TNF-α, CCL5 and CXCL-10." (PMID 39795906, 2024). "There has been extensive work using cell lines and mast cells derived from human cord blood that has shown FcγRII-dependent enhancement of infection, upregulation of CCL3, CCL4, CCL5, IL-1β, and IL-6, and TNF-α-mediated endothelial activation." (PMID 38793609, 2024). "We observed that concentrations of the monocyte chemoattractants CCL2, CCL3, CCL4, CCL5, and CCL7 were significantly increased in mice inoculated with both pathogens, relative to vehicle and single Bb infection." (PMID 39229265, 2024). "Infection of the cornea with ZIKV leads to the synthesis of the IL-1β, TNF-α, CCL5, and CXCL-10 which recruits other cells of the immune system to the cornea and this promotes inflammation and damage to corneal tissue leading to keratitis." (PMID 39795906, 2024). "Infection with NCTC10562 was seen to induce a variety of inflammatory cytokines and chemokines including IP-10, RANTES/CCL5 and MCP-1/CCL2." (PMID 39286811, 2024). "Spinal cords of wild-type mice contained significantly higher levels of IFN-β and IL-6 at day 5 post-infection (p ≤ 0.05) and IFN-γ, IL-1β, CCL3, CCL5, and CXCL9 at 5 and 9 days post-infection (p ≤ 0.05)." (PMID 39339840, 2024). "Cytokine analysis indicated CCL5 (RANTES), CXCL9 (MIG), CCL4 (MIP-1B), and IFN-y peak between day 1 and 2 post infection dependent on the route of infection." (PMID 39734493, 2024). "Following the apical infection of hBLEC with both RVFV strains, we observed upregulation of three inflammatory cytokines, i.e., CCL5, CXCL9, and CXCL10, in the apical compartment." (PMID 39345143, 2024). "MVA∆E5R infection of BMDCs potently upregulated Ifnb1, Ifna, Ccl4, and Ccl5 gene expression, whereas MVA infection had modest induction." (PMID 37217469, 2023). "The expressions of CCR5 (the receptor of CCL3, CCL4, and CCL5) and CCRL2 (expressed on neutrophils and primary monocytes) were significantly down-regulated by the WT infection." (PMID 37513744, 2023). "Reduced expression of interferon-responsive genes, IL-6, IL-1, IL-1, CCL5, and TNF-, was evidence that TLR3 signaling was downregulated during a live MPOX infection." (PMID 37533932, 2023).
infection (continued). "We examined secreted protein levels of IFN-β, CXCL10, CXCL11, CCL5, and IDO in two male and two female primary HLMVEC donors at 48 and 60 h post infection." (PMID 37766212, 2023). "Monocytes are recruited to the site of infection during the early phase by IL-6, IL-8, CCL2, CCL5, and MIP-1α derived from infected AECs and macrophages." (PMID 37896776, 2023). "Here, we also show that USUV and WNV BBB direct infection led to the release of potent chemoattractants such as CXCL10, CCL5 and CCL2 in vitro and in vivo." (PMID 36495563, 2023). "Hantavirus species comparative studies performed in HUVECs show similar gene expression profiles for CCL5 during HTNV and PHV infection, whereas both CXCL10 and CXCL11 transcript levels are expressed the highest following infection of HTNV followed by PHV." (PMID 37766212, 2023). "Upon infection with influenza viruses, CCR5 and its cognate chemokines CCL3, CCL4, and CCL5 are induced rapidly, which contributes to leukocyte recruitment into the airways and a consequent efficacious antiviral response." (PMID 37041527, 2023). "Infection with this bacterium was shown to increase the production of IFN-γ, TNF-α, and chemokines such as CCL3, CCL4, CCL5, CCL11, and CXCL1." (PMID 38139161, 2023). "In response to inflammatory stimuli to the chemokines CCL11 (eotaxin-1), CCL24 (eotaxin-2), and CCL5 (RANTES), eosinophils migrate to inflamed tissues or to sites of infection where their survival is prolonged." (PMID 37483591, 2023). "The concentrations of chemokines, including CCL2, CCL5, and CXCL10, were all markedly reduced in the lungs of the AHCC-fed group at day 4 post infection (p < 0.05 or p < 0.01)." (PMID 37111440, 2023). "Conversely, infection significantly reduced levels of IL-1α, IL-2, IL-9, IL-10, IL-12 (p70), IL-13, IFNγ, IL-3, CCL4 (MIP-1β), CSF 2 (GM-CSF), CCL5 (RANTES), and TNFα." (PMID 37790429, 2023). "Chemoattractants like CCL5 or MIP-1α, secreted by RSV-infected AECs, lead to the recruitment of eosinophils to the site of infection." (PMID 37896776, 2023). "Infection of ALI-differentiated AEC infected with RV-A16 elicited robust production of IP-10, C-C motif chemokine ligand 5 (CCL5), and CXC motif chemokine ligand 8 (CXCL8)." (PMID 37773065, 2023). "Results showed that infection of virulent isolate Benin97/1 significantly increased expression not only of CCL2, but also of CCL3, CCL4 and CCL5, although the greatest fold increase was observed for CCL2." (PMID 36680273, 2023). "By day 2 after infection, significant elevations in the levels of interleukin-1β (IL-1β), TNF-α, IL-6, IFN-γ, IFNα, IFNβ, CXCL1, CCL2, and CCL5 were detected in the airways of influenza virus–infected mice." (PMID 37683004, 2023). "This was paralleled by an increase of chemokines (CCL-2, CCL-5, CXCL-10, IL-8) to attract immune cells to the site of infection, contributing to inflammation and tissue damage." (PMID 35788177, 2022). "ELISA analysis of supernatants confirmed that VACV∆C7L infection resulted in the secretion of IFN-β, CCL4 and CCL5 from WT AECIIs." (PMID 35351885, 2022). "Chemokines, such as CCL5, recruit CD4 T cells to sites of infection, where cytokines, such as IL-12 produced by DCs initiate the differentiation of CD4 T cells towards a Th1 subtype, producing IL-2 and IFN-γ." (PMID 36211447, 2022). "COV patients showed also lower levels of molecules able to recruit neutrophils in the site of infection, such as CXCL2 and CCL5." (PMID 35710943, 2022). "The chemokine CCL5 (RANTES) is mainly produced in lymphocytes and facilitates further recruitment of lymphocytes to the side of infection by increasing adhesion of leukocytes to the endothelium." (PMID 35359920, 2022). "The chemokine receptor CCR5 binds RANTES (CCL5), MIP1-alpha (CCL3), and MIP1-beta (CCL4) cytokines and plays a role in mounting an inflammatory response to infection." (PMID 35948929, 2022).
infection (continued). "In WT lung epithelial cells, infection with VACV∆C7L induced higher expression levels of Ifnb1, Ccl4, and Ccl5 compared with WT VACV." (PMID 35351885, 2022). "In response to ocular HSV-1 infection, pro-inflammatory cytokines including IL-1, IL-6 and chemokines including CCL2, CCL3, CCL5, CXCL1, CXCL2, CXCL9, and CXCL10 are produced rapidly following infection by resident cells and infiltrating leukocytes." (PMID 36685562, 2022). "The effect of the combination of CCL5 5p12 5m-C37 with the CCR5 antagonist MVC and, separately, with TDF (a nucleotide analogue reverse transcriptase inhibitor) was investigated in acute infection inhibition experiments." (PMID 36366513, 2022). "A CCL5-based CCR5 antagonist, CCL5 5p12 5m, has been developed that presented an in-vitro 1,000-fold increase in inhibiting HIV-1 cellular infection as compared to MVC." (PMID 36341422, 2022). "We confirmed a MDA5/STING-dependent upregulation of cytokine and chemokine genes after VACV∆C7L infection in AECII cells, including Ifnb1, Ccl2, Ccl7, Ccl4, Ccl5, and Cxcl10." (PMID 35351885, 2022). "RNA expression for CCL3, CCL4, CCL5 and CCL2 have been shown to persist into the latent stage of ocular HSV1 infection, i.e., longer than 30 days post infection." (PMID 36211447, 2022). "Upon Tha and Th2P-4M infection, foetal pAstrocytes strongly induced the expression of IFIH1, CCL5, and CXCL10, whereas hiMicros strongly upregulated expression of CXCL10 and genes coding for antiviral proteins ISG15 and MX1." (PMID 36680128, 2022). "On the other hand, CCL5/RANTES plasma levels were decreased during the acute phase of infection when compared to HD, and increased levels were found in the chronic phase of infection." (PMID 35456119, 2022). "Various inflammatory cytokines such as TNF (TNF), some ILs (IL1α, IL1β), and chemokines (including CCL2, CCL4, CCL5, CXCL8) were significantly up-regulated under all observation points after YC-2020 infection." (PMID 36338035, 2022). "Expression levels of IL-1β, RANTES (CCL5), IP-10, eotaxin (CCL11), KC, MCP-1, MIP-2, and MIG were significantly lower in MET + PCV vs. control + PCV group at 7 days post-infection (all p < 0.05)." (PMID 35821804, 2022). "Per bin, the intron counts of the infection-induced genes IFIT2, OAS2, CCL5, IL6, NFKBIA, and TNF are shown, along with ATXN10 as control." (PMID 33585804, 2021). "Here, we corroborate these findings in Calu-3 cells using an unbiased genome-wide methodology showing that antiviral cytokines (IFNL1-3, IFNB1, CCL5, CXCL11 and IL6) are restricted in translation at 24 h post infection." (PMID 33806254, 2021). "In control animals, we noted a significant increase in proinflammatory cytokines (IL-1α, IL-1β, IL-6, and TNF-α), and chemokines (RANTES/CCL5 and CXCL1) coupled with the surge of G-CSF in response to infection." (PMID 33514747, 2021). "Several chemokines were induced quickly in the early phase (day 2 p.i.)and maintained at a rather high level through the first week of infection, including CCL2, CCL3, CCL4, CCL7, CXCL10, IL-6, IFN-γ, CCL11, CCL5, TNF-α, CXCL1, IL-4, IL-12p70." (PMID 34379705, 2021). "The expression levels of CCL3, CCL5, CXCL10 and CX3CL1 in the brain tissue of infected mice was elevated with the extension of infection time." (PMID 34017692, 2021). "In the cases of CCL5 and CD3E, these regulatory molecules appear to be dysregulated by these miRNAs during infection, likely contributing further to EVD pathogenesis and fatal outcome." (PMID 33806942, 2021). "In our study, cytokines, such as MIP-1α/β, RANTES/CCL5, MDC/CCL22, KC/CXCL1, and LIX/CXCL5 were upregulated after infection." (PMID 35126335, 2021). "The amount of soluble CXCL10, CCL5, and IL6 was increased in the supernatant of infected astrocytes at 2 dpi, but it varies depending on the isolates used for infection similarly to the results obtained by RT-qPCR." (PMID 33407600, 2021).